YTHDF1 (YTH N6-methyladenosine RNA binding protein F1)
Diseases named in the same sentence as YTHDF1 in open-access papers (continued):
Sharing a sentence is not in itself a finding about the gene and the disease.
tumor (382 papers, 2018 to 2026). "By contrast, Ythdf1-deficient DCs display reduced lysosomal degradation, improved cross-presentation, and enhanced anti-tumor immunity." (PMID 41403953, 2025). "The METTL16 abundance has been found increased in cholangiocarcinoma tissues and its deficiency inhibits cell proliferation and tumor progression by reducing YTHDF1-mediated translation process of target mRNA PRDM15." (PMID 40734692, 2025). "In YTHDF1-deficient mice, increased cross-presentation of tumor antigens by DCs strengthens CD8+ T cell activation and antitumor responses." (PMID 40034695, 2025). "Pan-cancer analysis revealed that RNA methylation genes ALYREF, NSUN4, TRMT6, and YTHDF1 were associated with immune infiltration in the tumor microenvironment." (PMID 41244907, 2025). "High expression levels of YTHDF1 are associated with more aggressive tumor progression and poorer overall survival." (PMID 40271153, 2025). "Loss of Ythdf1 enhances anti-tumor immunity, reduces MDSCs, and increases cytotoxic T-cell responses, whereas overexpression promotes an immunosuppressive TIME." (PMID 41403953, 2025). "Significantly, this connection exhibits a positive relationship with CD4+ T cells while displaying a negative relationship with CD8+ T‐cell infiltration, thereby indicating an association between YTHDF1 and the tumor microenvironment (TME)." (PMID 39821576, 2025). "In xenograft models, mutating the O-GlcNAcylation site of YTH domain family 1 (YTHDF1) reduced tumor growth." (PMID 39285476, 2024). "By binding to lysosomal protease‐encoding transcripts with m6A marking, YTHDF1 improves the translation of these transcripts in DCs while preventing the cross‐presentation of endogenous tumour antigens and CD8+ T‐cell anti‐tumour responses." (PMID 39135292, 2024). "YTHDF1 expression was linked with tumor purity (r = 0.152, p = 1.44 × 10−6), B cells (r = 0.07, p = 2.96 × 10−2), CD8+ T cells (r = 0.175, p = 3.53 × 10−8), CD4+ T cells (r = 0.089, p = 2.96 × 10−2)." (PMID 38339157, 2024). "It has also demonstrated that loss of YTHDF1 in classical dendritic cells enhances the cross‐presentation of tumor antigens and CD8+T cell antitumor response through the recognition of methylated transcripts encoding lysosomal proteases." (PMID 38721006, 2024). "Methionine or YTHDF1 deficiency can inhibit tumour growth and synergise with PD‐1 blockade to improve anti‐tumour immune therapy by restoring CD8+ T‐cell cytotoxicity." (PMID 39135292, 2024). "In tumour immunity, YTHDF1‐deficient mice show enhanced T‐cell responses, resulting in a stronger anti‐tumour CD8+ T‐cell response." (PMID 39135292, 2024). "Limited data are available regarding the antitumor role of YTHDF1 in immune cells; the loss of Ythdf1 in dendritic cells (DCs) has been reported to inhibit tumor growth in murine cancer models." (PMID 39325547, 2024). "The loss of YTHDF1 inhibits tumor growth is due to increased infiltration of tumor-specific CD8+ T cells in the cancer tissue." (PMID 39457524, 2024). "High expression of YTHDF1 is associated with more aggressive tumor progression and poor prognosis in GC." (PMID 39185313, 2024). "In murine models, YTHDF1 deficiency can enhance antigen-specific CD8+ T-cell anti-tumor response as well as improve the therapeutic efficacy of anti–PD-L1 antibody." (PMID 37063837, 2023). "Our findings uncover the role of tumor-intrinsic YTHDF1 in driving immune evasion and elucidate its underlying mechanism." (PMID 36650153, 2023). "Loss of YTHDF1 enhances the cross-presentation of tumor antigens by decreasing translational efficiency of cathepsins, thus creating a favorable antitumor immune microenvironment." (PMID 37928272, 2023). "Nevertheless, analysis of the TCGA database has revealed mutations in YTHDF1 across multiple tumor types." (PMID 38202722, 2023). "Mechanistically, the knockdown of YTHDF1 promotes cross-presentation of tumor-associated antigens by DCs, which activate CD8+ T cell-mediated adaptive immune response." (PMID 36650570, 2023).
tumor (continued). "Alterations in the expression of m6A writers (i.e. METTL3 and METTL14), erasers (i.e. FTO) or readers (i.e. YTHDC2 and YTHDF1), for example, are associated with tumor-suppressive or tumor-promoting scenarios." (PMID 36866275, 2023). "Overall, single-cell sequencing analysis revealed that tumor-intrinsic YTHDF1 deficiency promoted the infiltration of antitumor immune cells and reduced tumor-promoting immune cells via TME remodeling." (PMID 36650153, 2023). "Our findings elucidate the role of tumor-intrinsic YTHDF1 in driving immune evasion and its underlying mechanism." (PMID 36650153, 2023). "Evidence from experimental studies observed that the infiltration levels of CD8+T increased in YTHDF1-deficient mouse tumour, thereby enhancing an elevated antigen-specific CD8+T cell antitumor response in vivo." (PMID 36936424, 2023). "The loss of YTHDF1 in classic DCs can significantly enhance the cross‐presentation of tumor antigens and the cross‐activation of CD8+ T cells, which regulates durable neoantigen‐specific immunity." (PMID 37090117, 2023). "In conclusion, abundant evidence has established a close association between YTHDF1 and tumor progression." (PMID 38202722, 2023). "Mechanistically, YTHDF1 deficiency suppressed cancer NSCLC progression and in vivo tumor growth via YTHDF1/Keap1-Nrf2-AKR1C1 axis." (PMID 36707507, 2023). "In our study, YTHDF1 deficiency significantly promoted tumor MHC-I expression and subsequently led to an enhanced T-cell recognition as evidenced by the increased infiltration of CD4+ and CD8+ T cells, and expanded TCR clone type in the TME." (PMID 36650153, 2023). "Loss of YTHDF1 in DCs enhances the cross-presentation of tumor antigens and the cross-activation of CD8+ T cells in vivo." (PMID 35254013, 2022). "For instance m6A deficiency will lead to the disability of some anti-tumor immune cells, whereas YTHDF1 deficiency enhances anti-tumor immune responses." (PMID 36138023, 2022). "Genetic ablation of YTHDF1 in mice leads to reduced tumor growth associated with increased tumor infiltration by cytotoxic T cells, whilst simultaneously reducing infiltration of myeloid-derived suppressor cells (MDSC)." (PMID 35884552, 2022). "In order to identify the tumor immune microenvironment associated with the expression of YTHDF1 or YTHDF2, the association between such expression and immune checkpoints other than PD-1/PD-L1 was investigated." (PMID 36479088, 2022). "Loss of YTHDF1 in tumor cells leads to the recruitment of mature DCs in the tumor, which in turn promotes the infiltration of T helper cells and cytotoxic T cells, as well as the increased production of cytotoxic cytokines." (PMID 35884552, 2022). "Consistently, loss of YTHDF1 caused a significant decrease in both tumor size and tumor weight as compared with control." (PMID 35193930, 2022). "Analysis of tumor infiltrating immune cells showed that loss of YTHDF1 promoted the recruitment of mature dendritic cells (DCs), which contributed to increased homing of CD4+ and CD8+ T-cells to tumors." (PMID 35193930, 2022). "For example, METTL3-mediated m6A modification physiologically promotes activation of dendritic cell (DC) and DC-based T cell responses, and loss of YTHDF1 enhances CD8+ T cell tumor infiltration, making anti-PD-L1 therapy more effective." (PMID 35186164, 2022). "Higher expression of YTHDF1 was strongly associated with OS patients’ tumor diameter, TNM staging, and distant metastasis." (PMID 35156522, 2022). "Genetic ablation of YTHDF1 in mice leads to reduced tumor growth associated with increased tumor infiltration by cytotoxic T cells while simultaneously reducing infiltration of myeloid-derived suppressor cells (MDSCs)." (PMID 36713584, 2022). "It is demonstrated that YTHDF1 is essential for durable neoantigen-specific immunity, and YTHDF1-deficient mices show an elevated antitumor response of tumor-infiltrating CD8+ T cell." (PMID 36035161, 2022).
tumor (continued). "In particular, high expression of YTHDF1 is associated with poor overall survival and malignant tumour behaviours in CRC." (PMID 36551532, 2022). "In dendritic cells, loss of YTHDF1 enhanced the cross-presentation of tumor antigens and the cross-priming of CD8(+) T cells in vivo." (PMID 35806168, 2022). "Collectively, these results suggest that loss of YTHDF1 in tumor cells leads to the recruitment of mature DCs in the tumor, which in turn promote infiltration of T helper cells and cytotoxic T cells, and increased the production of cytotoxic cytokines." (PMID 35193930, 2022). "YTHDF1 overexpression was also associated with advanced pM stage (p < 0.001) and tumor size >5 cm (p < 0.001)." (PMID 36347025, 2022). "Targeting YTHDF1 holds therapeutic potential, as the overexpression of YTHDF1 is associated with tumor resistance to chemotherapy and immunotherapy." (PMID 35884552, 2022). "The correlation between YTHDF1 and tumor mutational burden (TMB), microsatellite instability (MSI), and neoantigens also proved that YTHDF1 closely related with the TME in human cancers." (PMID 34026603, 2021). "Previously studies have demonstrated that m6A modification plays a critical role in HCC progression and the shaping of TME, e.g., YTHDF1 promotes tumor progression and was closely associated with poor prognosis." (PMID 34277630, 2021). "YTHDF1 is mutated in approximately 7 % of patients with GC, and high expression of YTHDF1 is associated with more aggressive tumour progression and poorer overall survival." (PMID 34246319, 2021). "Since YTHDF1 plays a more important role in promoting HCC autophagy under hypoxia, and autophagy is reportedly associated with tumor malignancy, we further investigated the tumor-promoting role of YTHDF1 and its relationship with autophagy." (PMID 33619246, 2021). "Loss of YTHDF1 facilitated the cross-presentation of tumor antigens on dendritic cells (DCs) and increased cross-priming of CD8+ T cells." (PMID 33928028, 2021). "In a CC-bearing mouse model, YTHDF1-deficient mice showed tumor growth inhibition and survived longer than wild-type mice." (PMID 34956201, 2021). "Low YTHDF1 expression lead to delayed cell growth of BGC-823-engrafted tumors, and the tumor weight and volume in YTHDF1 deficient tumors were reduced in comparison with the sh-NC group." (PMID 33791305, 2021). "Recently, it is reported that the loss of m6A reader YTHDF1 in DCs enhances antitumor immunity and inhibits tumor growth in mouse models." (PMID 34103054, 2021). "The loss of YTHDF1 in classical dendritic cells enhanced the cross-presentation of tumor antigens and the cross-priming of CD8+ T cells in vivo." (PMID 34956201, 2021). "YTH N6-methyladenosine RNA binding protein 1 (YTHDF1) was found to be positively associated with aggressive tumor progression and poor overall survival by promoting the translation of the essential Wnt receptor frizzled 7 (FZD7) in an m6A-dependent manner." (PMID 33816259, 2021). "A recent article on a mouse model reports that m6A-modified mRNAs encoding lysosomal cathepsins are recognized by YTHDF1 in dendritic cells (DCs), subsequently enhancing the translation of cathepsins and facilitating tumour growth and shortening host survival." (PMID 33654093, 2021). "Dali and colleagues demonstrated that the cross-presentation of tumor antigens and the cross-priming capacity of tumor-associated DCs are enhanced in Ythdf1−/− mice." (PMID 33746967, 2021). "Specifically, the deficiency of YTHDF1 elevated the cross-presentation of tumor antigens and antigen-specific CD8 + T cell antitumor response." (PMID 34482808, 2021). "Up-expression of YTHDF1 was significantly associated with N stage (TCGA cohort, P = 0.019), cancer lesion (GEO cohort, P = 0.002), and tumor size (TMA1, P = 0.015) in patients with GC." (PMID 33791305, 2021).
tumor (continued). "Consistent with a relationship between m6A level and tumor immunity, m6A modification of mRNA and expression of YTHDF1 in dendritic cells have been associated with antitumor immunity." (PMID 34307344, 2021). "The correlation heatmap showed that YTHDF1 H-score was positively associated with cyclin B1 H-score (R = 0.25, p = 0.03) and tumor size (R = 0.38, p = 0.001)." (PMID 34359836, 2021). "Loss of YTHDF1 promotes DC-mediated cross-presentation of tumor antigens and cross-priming of CD8+ T cells in vitro and in vivo." (PMID 34616742, 2021). "Mechanistically, YTHDF1 recognizes m6A-modified transcripts encoding lysosomal cathepsins in DCs and promotes their translation, which inhibits the cross-presentation of tumor neoantigens to achieve immune escape." (PMID 33928028, 2021). "Recent findings also showed that YTHDF1-deficient mice show an elevated antigen-specific CD8(+) T cell anti-tumor response." (PMID 33204330, 2020). "By thoroughly investigating the role of YTHDF1 deregulation in HPSCC, we found that YTHDF1 is closely associated with tumor proliferation and iron metabolism." (PMID 33204330, 2020). "They demonstrated that loss of YTHDF1 in classical DCs enhanced the cross-presentation of tumor antigens and the cross-priming of CD8+ T cells in vivo by binding to lysosomal protease transcripts and increasing their translation." (PMID 31015515, 2019). "Immunostaining of Ythdf1 showed that its expression was associated with various malignant tumor behaviors, such as depth, lymph node metastasis, and poorer cancer stages." (PMID 29484125, 2018). "When we analyzed the associations between YTHDF1 expression and clinical parameters, high expression of YTHDF1 was associated with female sex, older age, and lymphatic metastasis in both central and peripheral tumor regions." (PMID 39587835, 2025). "Therapeutic strategies aimed at restoring YTHDF1 function or reducing TSC22D1 expression may suppress tumor growth, particularly in EBV-associated gastric cancer (EBVaGC), which currently lacks targeted therapies." (PMID 41472023, 2025). "Furthermore, tumor-intrinsic YTHDF1 deficiency demonstrated synergistic effects with anti-CTLA-4 or anti-PD-L1 antibodies, leading to reduced tumor volume and extended overall survival in mice bearing B16/F10 cells." (PMID 39987091, 2025). "Through its impact on the translation of mRNAs encoding factors involved in immune cell trafficking, YTHDF1 can promote the accumulation of immune-suppressive cells like M2 macrophages and Tregs, while simultaneously inhibiting the activation of anti-tumor T cells." (PMID 39911396, 2025). "Similarly, YTHDF1‐deficient mice in a colon cancer model exhibit suppressed tumour growth and prolonged survival due to the stronger potential of DCs to cross‐present tumour antigens." (PMID 39135292, 2024). "In tumor immunity, YTHDF1-deficient mice have increased dendritic cell capacity to present tumor antigens, resulting in increased immune response initiation by T cells and a stronger anti-tumor CD8+ T cell response." (PMID 38339157, 2024). "Furthermore, we explored YTHDF1′s functions in the tumor mutational burden, microsatellite instability, and tumor microenvironment." (PMID 38339157, 2024). "To assess whether distinct DC subpopulations are implicated in antitumor effects of IR in Ythdf1-cKO mice, we profiled the B16-OZ tumor–infiltrating DCs by flow cytometry." (PMID 39325547, 2024). "YTHDF1 also exerts its effects in tumor-associated macrophages." (PMID 38202722, 2023). "In addition, YTHDF1-deficient DC cells can enhance tumor antigen presentation and the anti-tumor capacity of CD8+ T cells." (PMID 37020540, 2023). "In this study, we aim to (i) validate the function of tumor-intrinsic YTHDF1 in driving immune evasion and elucidate its underlying mechanism, (ii) analyze the association between YTHDF1 expression and response to ICI therapy, and (iii) exploit efficient strategies that block YTHDF1 in vivo." (PMID 36650153, 2023).
tumor (continued). "Strikingly, ablation of METTL3 in myeloid cells promoted tumor growth and metastasis, associated with decreased YTHDF1-mediated translation of SPRED2 and increased activation of NF-kB and STAT3 through the ERK pathway, leading to increased tumor growth and metastasis." (PMID 37369946, 2023). "Furthermore, YTHDF1 plays a tumor-promoting role by facilitating mitosis-associated RANBP2 mRNA translation in an m6A-mediated approach, while YTHDF2 exerts the same role by degrading the tumor suppressor GAS5 mRNA." (PMID 36999016, 2023). "To comprehensively elucidate the mechanism of tumor-intrinsic YTHDF1 deficiency in the induction of antitumor immunity, we initially performed proteomics to reveal the alteration of intrinsic proteins and pathways between B16/F10 WT (n = 5) and KO (n = 5) groups." (PMID 36650153, 2023). "In xenograft models, the O-GlcNAc–deficient YTHDF1-AFA mutants attenuated tumor progression, suggesting that OGT could regulate many more downstream substrates to promote cancer growth." (PMID 37086786, 2023). "High expression of YTHDF1 in human colon tumour cells causes cisplatin resistance through the enhancement of glutaminase synthesis, and inhibition of glutaminase synergizes with the tumour-suppressing effect of cisplatin." (PMID 36859310, 2023). "Moreover, YTHDF1 was also to be proved positively associated with tumor size, lymph node invasion and distant metastasis of cancer." (PMID 36707507, 2023). "Moreover, Kaplan–Meier survival analysis revealed that GC patients with a high YTHDF1 expression had a poor overall survival (OS) rate (P = 0.0352) and a higher risk of tumor recurrence." (PMID 36561529, 2022). "In addition to the tumor cell intrinsic effects of YTHDF1, we also revealed that loss of YTHDF1 in GC tumors induced antitumor immunity in syngeneic models, leading to tumor complete remission." (PMID 35193930, 2022). "YTHDF1 deficiency in classical dendritic cells could enhance antigen presentation, initiate anti-tumor responses, and improve the therapeutic effectiveness of PD-L1 checkpoint blockade." (PMID 36591468, 2022). "In addition, YTHDF1 deficiency in DCs intensifies the early steps of T cell priming against tumor neoantigens." (PMID 35254013, 2022). "Mechanistically, the deletion of YTHDF1 could promote cross-presentation of tumor-associated antigens by DCs, which activate CD8+ T cell-mediated adaptive immune response." (PMID 35884552, 2022). "Besides, YTHDF1 overexpression is associated with changes in the tumor microenvironment that are favorable to tumorigenesis." (PMID 35884552, 2022). "With regard to the mechanism that caused the infiltration of mature DCs, we demonstrated that loss of YTHDF1 in tumor cells could increase the expression of IFNGR1 in tumor cells." (PMID 35193930, 2022). "Moreover, high YTHDF1 expression is associated with more aggressive tumor progression and poor prognosis." (PMID 35884552, 2022). "Western blot confirmed that sgYTHDF1-1 tumor retained the loss of YTHDF1 protein." (PMID 35193930, 2022). "Since the potential target genes regulated by YTHDF1 might be associated with amino acid degradation and lipid metabolism in the tumor cell cycle, abnormalities in these physiological functions could lead directly to the occurrence and progression of HCC." (PMID 36017491, 2022). "Besides, from the analysis results of clinicopathological features, high expression of YTHDF1 was associated with advanced pM stage and tumor size >5 cm, while high expression of ALKBH5 was negatively associated with vascular invasion." (PMID 36347025, 2022). "Mechanistically, m6A-containing transcripts encoding lysosomal proteases are recognized by YTHDF1, and thus elevated expression at the translational level promotes the degradation of tumor neoantigens and represses cross-presentation to influence the efficacy of immunotherapy." (PMID 33795663, 2021).